EFTUD2 (elongation factor Tu GTP binding domain containing 2)
Diseases named in the same sentence as EFTUD2 in open-access papers (continued):
Sharing a sentence is not in itself a finding about the gene and the disease.
Burn-McKeown syndrome (3 papers, 2019 to 2022). "Two of these disorders – mandibulofacial dysostosis Guion-Almeida type (MFDGA) and Burn-McKeown syndrome (BMKS) – are caused by variants in U5 snRNP proteins, EFTUD2 and TXNL4A, respectively." (PMID 33584830, 2021). "Interestingly, one downregulated gene in the EFTUD2-knockdown cell line was TXNL4A, the causative gene in Burn–McKeown Syndrome and another U5 snRNP protein." (PMID 31304552, 2019).
liver cancer (3 papers, 2020 to 2025). An epithelial or non-epithelial malignant neoplasm that arises from the liver. "When the expression level of EFTUD2 is reduced, it arrests the cell cycle of liver cancer cells and hinders the transition from the G1 to S phase." (PMID 40116087, 2025). "Thus, EFTUD2 is considered to be a potential therapeutic target for liver cancer." (PMID 40116087, 2025). "A recent study showed that the expressions of COPZ1 and EFTUD2 were significantly higher in tumor tissues compared with normal tissues and both two genes may correlated with poor prognosis of liver cancer based on the TCGA database." (PMID 34257558, 2021).
asthenozoospermia (2 papers, 2021 to 2025). "Li and Chen identified EFTUD2 as one of the genes with the highest connectivity degree in the differential gene network related to asthenozoospermia." (PMID 40116087, 2025). "They found that EFTUD2 expression was downregulated in patients with asthenozoospermia." (PMID 40116087, 2025).
CHARGE syndrome (2 papers, 2018 to 2023). CHARGE syndrome is a multiple congenital anomaly syndrome characterized by the variable combination of multiple anomalies, mainly Coloboma; Choanal atresia/stenosis; Cranial nerve dysfunction; Characteristic ear anomalies (known as the major 4 C's). "Some patients with GS have clinical findings that overlap with those of other syndromes, such as Treacher Collins syndrome, Townes–Brocks syndrome, CHARGE syndrome, Branchio-oto-renal spectrum disorders, and the phenotypic spectrum associated with mutations in EFTUD2." (PMID 30134872, 2018).
cognitive decline (2 papers, 2015 to 2018). "In addition, COPZ1 and EFTUD2 have been associated with cognitive decline in PD patients." (PMID 29896099, 2018). "Discriminant analysis showed that the best predictors of cognitive decline were EFTUD2, COPZ1, PTPN1, FAXDC2, MLST8 and age." (PMID 29896099, 2018). "Collectively, we report the association of three RNA biomarkers, COPZ1, EFTUD2 and PTBP1 with clinical features including cognitive decline in early drug-naïve PD patients." (PMID 26566043, 2015).
Cognitive impairment (2 papers, 2018 to 2025). Abnormal cognition is characterized by deficits in thinking, reasoning, or remembering. "Further analysis showed that relative expression of both EFTUD2 and PTBP1 was significantly downregulated in PD patients with cognitive impairment compared to PD patients with normal cognition." (PMID 29896099, 2018). "In addition, the combination of PTPN1, COPZ1, FAXDC2, EFTUD2 and MLST8 is a useful signature for cognitive impairment." (PMID 29896099, 2018).
developmental delay (2 papers, 2019 to 2020). "ES, which was performed at the age of 8 weeks, and following variant prioritization based on the phenotypic features of hearing loss, dysmorphology, and developmental delay, revealed a splice donor site variant of EFTUD2 (c.271+1G>A)." (PMID 32408545, 2020).
Parkinson disease (2 papers, 2015 to 2025). A progressive degenerative disorder of the central nervous system characterized by loss of dopamine producing neurons in the substantia nigra and the presence of Lewy bodies in the substantia nigra and locus coeruleus. "Santiago and Potashkin investigated 10 RNA biomarkers, including EFTUD2 and compared their expression levels between patients with Parkinson's disease (PD) and healthy controls." (PMID 40116087, 2025). "Further, COPZ1, EFTUD2 and PTBP1 mRNAs correlated with clinical features in PD patients including the Hoehn and Yahr scale, Movement Disorder Society revision of Unified Parkinson’s Disease Rating Scale (MDS-UPDRS) and Montreal Cognitive Assessment (MoCA) score." (PMID 26566043, 2015).
retinitis pigmentosa (2 papers, 2021 to 2025). Retinitis pigmentosa (RP) is an inherited retinal dystrophy leading to progressive loss of the photoreceptors and retinal pigment epithelium and resulting in blindness usually after several decades. "Variants in TXNL4A and EFTUD2 manifest in craniofacial malformations while variants in PRPF8 and SNRNP200 manifest in retinitis pigmentosa." (PMID 40264708, 2025).
atrial fibrillation (1 paper, 2025). A disorder characterized by an electrocardiographic finding of a supraventricular arrhythmia characterized by the replacement of consistent P waves by rapid oscillations or fibrillatory waves that vary in size, shape and timing and are accompanied by an irregular ventricular response. "The WMH TWAS also identified genes associated with AD (ARMS2), atrial fibrillation (NEURL and GJC1), innate immunity (EFTUD2), and apoptosis and neurodevelopment (PDCD7, FBXO31, and ClpX)." (PMID 40141087, 2025).
lentivirus infection (1 paper, 2020). Virus diseases caused by the Lentivirus genus. "Surprisingly, we also found that the stable knockdown of EFTUD2 expression via lentivirus infection was lethal for HCC cells." (PMID 33024090, 2020).
lung adenocarcinoma (1 paper, 2025). A carcinoma that arises from the lung and is characterized by the presence of malignant glandular epithelial cells. "Elongation Factor Tu GTP Binding Domain Containing 2 (EFTUD2), a conserved spliceosomal GTPase, is involved in craniofacial development and various cancers, but its role in lung adenocarcinoma (LUAD) remains unclear." (PMID 40236649, 2025).
lymph node metastasis (1 paper, 2025). "Analysis of bioinformatics data and clinical characteristics both revealed that elevated EFTUD2 expression in LUAD is correlated with age and N classification (i.e., local lymph node metastasis)." (PMID 40236649, 2025).
medulloblastoma (1 paper, 2025). A malignant, invasive embryonal neoplasm arising from the cerebellum. "Targeted ablation of Eftud2 in granule precursor cells (GNPs) within the cerebellum prolonged the survival of SHH-subgroup medulloblastoma mice, indicating a putative association between Eftud2 expression and medulloblastoma prognosis." (PMID 40275081, 2025). "Functional assays unveiled that EFTUD2 depletion in human medulloblastoma cells significantly curtailed cellular proliferation by impeding the activation of the SHH signaling pathway." (PMID 40275081, 2025). "This investigation delineated an upregulation of the spliceosomal protein Eftud2 in the SHH-subgroup medulloblastoma mouse model and human medulloblastoma patients." (PMID 40275081, 2025).
multiple myeloma (1 paper, 2024). "By validating CancerHubs predictions we demonstrated that TGOLN2 is a protein with tumour suppressor features in Multiple Myeloma, Breast and Prostate Cancer and that EFTUD2 has an oncogene-like behaviour in Multiple Myeloma." (PMID 39657701, 2024). "Through this approach, we identified TGOLN2 as a putative novel broad cancer tumour suppressor and EFTUD2 as a putative novel multiple myeloma oncogene." (PMID 39657701, 2024). "By exploring the data produced, we discovered several putative novel broad cancer and cancer-specific genes and validated two of them: TGOLN2, a putative novel broad cancer tumour suppressor and EFTUD2, a new putative oncogene in Multiple Myeloma." (PMID 39657701, 2024).
retinal degeneration (1 paper, 2019). Degeneration of the retina. "For example, why variants in the U5 snRNP genes PRPF6, PRPF8 and SNRNP200 are associated with retinal degeneration in adRP, while variants in the U5 snRNP genes EFTUD2 and TXNL4A are linked to craniofacial disorders, is not understood." (PMID 31304552, 2019).
testicular cancer (1 paper, 2021). A primary or metastatic malignant neoplasm that affects the testis. "As expected, EFTUD2, ELAVL2, HNRNPD, KIT, NCL, NRXN1 and RPS8 were significantly varied in testicular cancer patients." (PMID 33746583, 2021). "Among 25 hub genes, EFTUD2, HNRNPD, KIT, NCL and RPS8 were significantly upregulated in testicular cancer patients, however, ELAVL2 and NRXN1 were significantly downregulated using GEPIA online database." (PMID 33746583, 2021).
cancer (14 papers, 2015 to 2025). A tumor composed of atypical neoplastic, often pleomorphic cells that invade other tissues. "EFTUD2 is strongly expressed in colorectal cancer cells, and its deficiency in myeloid progenitor cells can inhibit cancer occurrence and progression." (PMID 40236649, 2025). "Elongation factor Tu GTP binding domain containing 2 (EFTUD2) has emerged as a potential oncogenic factor implicated in various cancer types, where it fosters tumor growth and survival." (PMID 38163859, 2024). "In general, EFTUD2 is strongly associated with cancer progression; however, the function of EFTUD2 in LUAD remains unknown." (PMID 40236649, 2025). "Consequently, further investigations into the underlying mechanism and biological function of the EFTUD2/c-MYC axis in cancer development are anticipated." (PMID 38163859, 2024). "This suggests that EFTUD2 may be an important potential risk factor in cancer development." (PMID 40236649, 2025). "Overall, these results validate the efficacy of CancerHubs predictions and establish TGOLN2 as a novel broad cancer hub with tumour suppressor-like properties and EFTUD2 as a novel MM hub with oncogenic properties." (PMID 39657701, 2024). "Only limited data are available examining the role of EFTUD2 in cancer and, to the best of our knowledge, this is the first study examining EFTUD2 in EC." (PMID 36068443, 2023). "Other studies have demonstrated that EFTUD2 performs a similar role, where depletion of EFTUD2 leads to enhanced apoptosis in developmental models and cancer cell lines." (PMID 36560714, 2022). "EEF2 is overexpressed in numerous cancer types and EFTUD2 knockdown induces apoptosis in breast cancer cells." (PMID 31575041, 2019). "In summary, the evidence linking EFTUD2 to poor prognosis in cancers suggests that it could serve as a valuable biomarker to predict patient outcomes." (PMID 40116087, 2025). "In addition to our clinical study, the TCGA results also demonstrated significant differences in EFTUD2 expression across the subgroups of pathologic N stage (N1 vs. N0), cancer stage (III vs. I), and smoking history (current smoker vs. previous smoker)." (PMID 40236649, 2025). "These diverse roles highlight the complex and context-dependent nature of EFTUD2 in cancer." (PMID 40650074, 2025). "Several recent studies have highlighted the role of EFTUD2 in cancer progression." (PMID 40236649, 2025). "Beyond its role in mRNA splicing, EFTUD2 appears to have broader functions in cancer development." (PMID 40650074, 2025). "Nonetheless, whether EFTUD2 is involved in regulating chemoresistance in different types of cancers, along with the precise molecular mechanisms of its action, remains to be understood." (PMID 40650074, 2025). "Furthermore, the role of EFTUD2 in shaping the tumor microenvironment through immune regulation presents potential therapeutic avenues for targeting EFTUD2 in cancer treatment." (PMID 40116087, 2025). "For experimental manipulation, we chose SW480, which displayed the lowest EFTUD2 expression among the cancer cell lines, for EFTUD2-overexpression experiments, while selecting Caco-2 and HCT116, both with higher EFTUD2 expression, for EFTUD2-knockdown experiments." (PMID 38163859, 2024). "Furthermore, recurrent somatic mutations or changes in the expression levels of a number of U5 snRNP proteins (PRPF6, PRPF8, EFTUD2, DDX23, and SNRNP40) have been associated with human cancers." (PMID 33584830, 2021). "However, somatic mutations in PRPF8 have now been linked to myeloid neoplasms, while altered expression levels of several other U5 snRNP proteins (PRPF6, EFTUD2, SNRNP40, and DDX23) have been associated with human cancer." (PMID 33584830, 2021). "Moreover, data from an in vivo lung metastasis model (established via tail vein injection of cancer cells) suggested that the overexpression of EFTUD2 led to increased lung metastatic nodules." (PMID 33024090, 2020).
cancer (continued). "Thus, the present study reviewed current research on EFTUD2 mutations and their clinical implications, focusing particularly on developmental abnormalities, innate immune responses and cancer progression, aiming to offer new insights into the diagnosis and treatment of EFTUD2-related diseases." (PMID 40116087, 2025). "Besides TGOLN2 and EFTUD2, our method predicted several other broad cancer or cancer-specific hubs." (PMID 39657701, 2024). "Just like EFTUD2 for MM, KIAA1429 was found to be a cancer-specific seed hub for BC, but also a broad cancer interactor hub, pointing to a broader cancer role for KIAA1429." (PMID 39657701, 2024). "Here, we validated two selected cancer-related genes from the seed lists: TGOLN2, a new broad cancer hub with tumour suppressor-like properties and EFTUD2, a novel MM-specific hub with oncogenic potential." (PMID 39657701, 2024). "Starting from the seed lists, we selected one broad cancer tumour suppressor-like gene and one cancer-specific gene with oncogenic potential to validate, namely TGOLN2 and EFTUD2." (PMID 39657701, 2024). "Although EC is known as an “immunogenic” cancer, this is—to the best of our knowledge—the first study examining RIG-I and EFTUD2 in EC." (PMID 36068443, 2023). "The authors concluded that overexpression of Eftud2 is involved in the pathogenesis of CAC by modulating the inflammatory response of macrophages, highlighting the link between inflammation, cancer and alternative splicing in the innate immune system." (PMID 33584830, 2021). "Interestingly, the analysis revealed that 7 targets (SF3B1, SF3B3, SNRPA, SNRPE, SNRPF, HNRNPA3 and EFTUD2) are physically interacting proteins within the spliceosome complex, suggesting that JA might regulate the cancer spliceosome to induce tumor-specific cell death." (PMID 28198434, 2017). "However, studies on COPZ1 and EFTUD2 in HCC are still few, but some studies have shown that COPZ1 and EFTUD2 are closely related to cancer development." (PMID 32537629, 2020). "In the present study, we noted that EFTUD2 was strongly expressed in LUAD tissues by using data from online databases and confirmed these results in patient LUAD tissue samples and cell lines—consistent with its expression patterns in colorectal, hepatocellular, and endometrial cancers." (PMID 40236649, 2025). "Intriguingly, despite EFTUD2 was found as a seed only in MM, the protein was present as a top scorer interactor hub also in BC, PrC, and CRC, suggesting that it might actually possess a broader cancer-related role." (PMID 39657701, 2024). "However, it has to be reminded that induction of apoptosis by SNW1 or EFTUD2 knockdown was not specific to cancer cells because depletion of either protein in normal mammary epithelial cells, MCF10A, also induced significant apoptosis (data not shown)." (PMID 25450007, 2015).
tumor (9 papers, 2017 to 2025). "An elevated level of EFTUD2 is also associated markedly with the prognosis of a variety of tumors and has the potential to be used as a tumor independent prognostic biomarker." (PMID 40116087, 2025). "Recent research has revealed that elevated EFTUD2 expression is closely linked to tumor growth and poor survival." (PMID 38163859, 2024). "Immunohistochemical analysis from the ccRCC validation cohort revealed that EFTUD2 expression is predominantly within the nuclei of tumor cells, while PROM1 is located in the cytoplasm." (PMID 40650074, 2025). "In vivo tumor xenograft experiments showed that after EFTUD2 knockdown, the TUNEL-positive cell rate increased, indicating enhanced cell apoptosis." (PMID 40236649, 2025). "The results revealed that, compared to the control group, lactate levels in both serum and tumor tissues of the EFTUD2 knockdown mice were significantly reduced." (PMID 40236649, 2025). "This evidence suggests that EFTUD2 and PROM1 gene expression have significant diagnostic potential in early tumor detection, potentially reflecting the trends in progression." (PMID 40650074, 2025). "We established a tumor xenograft model to investigate the role of EFTUD2 in mediating LUAD tumor growth in vivo." (PMID 40236649, 2025). "Our results demonstrated that EFTUD2 shaped the tumor immune microenvironment (TIME) and is closely related to genes involved in N6-methyladenosine (m6A) modification and the cyclic GMP-AMP synthase-stimulator of interferon genes (cGAS-STING) pathway." (PMID 40236649, 2025). "Our study emphasizes the promoting role of elevated EFTUD2 expression in the progression of LUAD, and also includes its diagnostic and prognostic value for the tumor." (PMID 40236649, 2025). "By monitoring the lactate levels in tumor tissues and serum in the later stages after tumor xenograft implantation in mice, we found that lactate levels in both serum and tumor tissues decreased following EFTUD2 knockdown." (PMID 40236649, 2025). "EFTUD2 was significantly upregulated in ccRCC, suggesting a potential involvement in tumor progression, while PROM1 was downregulated." (PMID 40650074, 2025). "This suggests that EFTUD2 is involved in regulating immune infiltration in HCC by promoting the formation of a tumor-favorable immune microenvironment." (PMID 40116087, 2025). "The wide range of EFTUD2 expression in tumor samples, from extremely high to extremely low, was further corroborated by IHC analysis, indicating heterogeneity within ccRCC." (PMID 40650074, 2025). "Further cellular and in vivo experiments are required to explore the mechanisms by which EFTUD2 influences the development and progression of this tumor." (PMID 40116087, 2025). "EFTUD2 is a potential diagnostic and prognostic marker for LUAD, associated with immune infiltration, the tumor microenvironment, the cGAS-STING pathway, m6A modification, and glycolysis." (PMID 40236649, 2025). "It is plausible that disruptions in EFTUD2-mediated splicing contribute to the dysregulation of gene expression programs critical for tumor suppression, leading to a more aggressive phenotype and poorer clinical outcomes." (PMID 40650074, 2025). "This reduction of inflammation and tumor development was related to an impaired activation of TLR-4-NF-κB signaling cascade in macrophages due to an altered EFTUD2 expression." (PMID 36068443, 2023). "Interestingly, we observed a substantial spread in EFTUD2 expression within tumor samples, with some specimens showing extremely high, and others extremely low, levels of this protein." (PMID 40650074, 2025). "Additionally, TUNEL assays on tumor samples revealed that, compared to tumors from control mice, the tumor regions in the EFTUD2 knockdown group exhibited increased apoptosis." (PMID 40236649, 2025). "Specifically, we found that EFTUD2 expression is predominantly within the nuclei of tumor cells." (PMID 40650074, 2025).